VIM (vimentin)
Diseases named in the same sentence as VIM in open-access papers (continued):
Sharing a sentence is not in itself a finding about the gene and the disease.
tumor (continued). "In contrast, when B7-H3 was knocked down in Caco-2 cells, the tumor displayed lower N-cadherin and Vimentin expression levels." (PMID 27145365, 2016). "Upregulation expression of vimentin in tumor cells was often close to and inside intratumoral vessels." (PMID 26231404, 2015). "The patient samples were also stained with anti-pan cytokeratin and anti-vimentin antibodies to specifically demarcate the tumor region from the stromal region respectively." (PMID 26306560, 2015). "In addition, vimentin and pan-cytokeratin staining served to differentiate between cell types, corroborating our morphological observations, which imply that the presence of tumor-associated fibroblasts is a fundamental requirement for the growth of tumor cells." (PMID 25885552, 2015). "We used the same tumor markers as before and included additional lineage markers such as Vimentin (stromal cells), CD45 (lymphocytes) and Epcam (epithelial cells)." (PMID 25514598, 2015). "Tumor cell invasion is regulated by miR-221/-222 through increasing vimentin expression and reducing E-cadherin by targeting TRPS1 (Trichorhinophalangeal syndrome type 1) gene as well." (PMID 25797271, 2015). "Corresponding cells from mouse replaced human tumour stromal and endothelial cells in second generation PDXs as demonstrated with mouse-specific vimentin and CD31 immunohistochemical staining." (PMID 26440065, 2015). "The immunohistochemistry and Western blot assays showed that both Zeb1 and Vimentin were down-regulated and E-Cadherin was up-regulated in tumours harvested from mice inoculated with the miR-144-A549-luciferase cells." (PMID 26395400, 2015). "On immunohistochemical analysis, the tumor cells are characteristically positive for vimentin (VMT) and often for cytokeratin (CK) and epithelial membrane antigen (EMA), but generally negative for skeletal muscle marker or S-100 protein." (PMID 25788994, 2015). "The cytokeratin / vimentin staining pattern of the parental tumor was typically maintained in 3D constructs although cytokeratin expression was observed more frequently in cells on renal ECM than in the PSS." (PMID 26317980, 2015). "In contradiction to our findings, vimentin expression in HCC tumour cells has been reported by different authors working on Asiatic cohorts." (PMID 26110787, 2015). "Immunohistochemistry (IHC) revealed that the majority of tumor cells in Slu-01/AEG-1 xenotransplants strongly expressed Vimentin, but exhibited weak staining of E-cadherin." (PMID 25880337, 2015). "SHG139 in the 20th and 60th generations had the same molecular markers and cell morphology: GFAP, S-100 and Vimentin were expressed, and tumor cells were diploid or polyploid." (PMID 25879429, 2015). "The tumor cells displayed diffuse positivity for vimentin, inhibin, synaptophysin, and neuron-specific enolase (NSE)." (PMID 26376405, 2015). "As seen in vitro, the tumor cells developed from 12 T showed increased expression for Vimentin compared to CSM cells." (PMID 26597727, 2015). "Additional histological analysis of tumours revealed reduced Vimentin expression in line with the reduced tumour mass." (PMID 26132659, 2015). "Taken together, our results suggested that MEK5/ERK5 signalling promotes NF-κB activation and Vimentin expression, which contribute to increased tumour cell migration." (PMID 25855966, 2015). "Immunohistologically, tumor cells were positive for vimentin, alpha 1-antitrypsin, and alpha 1-antichymotrypsin, and partially positive for alpha-smooth muscle actin (SMA) and CD68/kp-1." (PMID 26366352, 2015). "vimentin was diffusely positive in the tumor cells, which supports but cannot fully prove the tumor as a mesenchymal neoplasm." (PMID 26315812, 2015). "Immunohistochemical staining revealed the tumor cells to be positive for vimentin, smooth muscle actin, and collagen type IV." (PMID 26697255, 2015).
tumor (continued). "In patients with CRC liver metastases the tumor stroma Hsp27+ vimentin+αSMA+ fibroblasts were less evident than in pulmonary metastases." (PMID 25793600, 2015). "This concept was supported by the activation of β-catenin and the low levels of E-cadherin in stem-like tumour cells at the tumour-host interface and the induction of mesenchymal markers in CSCs, such as vimentin and N-cadherin." (PMID 25708542, 2015). "Thereafter, we also analyzed the expression patterns of E-cadherin and Vimentin in these tumor samples from nude mice." (PMID 26068968, 2015). "These invasive tumor cells show reduced E-cadherin staining, with notable increases in both phospho-Src and vimentin that represent a more mesenchymal invasion modality." (PMID 25734659, 2015). "Tumors with lower content of ALDH1-positive stromal cells were also characterized more frequently by vimentin expression, indicating a mesenchymal phenotype and increased migratory abilities of tumor cells." (PMID 26305673, 2015). "The inverse correlation between ALDH1A2 and vimentin expression in tumor cells was further supported in a mouse xenograft model in vivo and tumor sections from OPSCC patients." (PMID 26634247, 2015). "Immunohistochemically, the tumor cells were positive for vimentin with strong coexpression of pancytokeratin in part of the cell population." (PMID 25877069, 2015). "For the tumor cell lines used however, vimentin staining is very low and is only obvious for the MC spheroids." (PMID 26208323, 2015). "Immunohistochemistry revealed that the tumor cells reacted with pan-cytokeratin immunostains and expressed vimentin and S-100 protein, collectively supporting the pathological diagnosis of primary EACC." (PMID 26943443, 2015). "The Vimentin protein has been positively related to the high metastasis of tumor cells and lymphocytes." (PMID 25889491, 2015). "Conversely, the expression of Vimentin was found to be lower in tumor samples derived from NVP-LDE-225 or NVP-BEZ-235 treated mice, and even lesser in tumors where combination of these drugs was used." (PMID 26451606, 2015). "The colonized CRC tumours had reduced levels of the epithelial cell marker E-cadherin but increased levels of the mesenchymal markers, N-cadherin and vimentin, suggesting an induction of epithelial-mesenchymal transition (EMT) in the process of colonization." (PMID 26234763, 2015). "As expected, highly expressed ETV4 in CRMAC increased MMP-7, N-cadherin and vimentin whereas decreased E-cadherin, which promoted tumor invasion." (PMID 26356816, 2015). "The suppression of vimentin expression in tumor tissue was also observed via immunohistochemical staining." (PMID 26160837, 2015). "We analyzed tumor invasive potential by performing western blot analysis on tumor tissue to determine the expression levels of vimentin, MMP-9 and both the pro-form and the proteolytically processed activated form of MMP-2." (PMID 26083629, 2015). "In a subpopulation (circa 10%) of vimentin positive tumor cells, however, E-cadherin was slightly decreased." (PMID 26041890, 2015). "Vimentin is an important protein constituent of cellular intermediate filaments in normal and tumor mesenchymal cells." (PMID 26095281, 2015). "After a few days, cells that migrated from the tumour tissues exhibited a fibroblast-like phenotype as confirmed by the expression of vimentin and were considered ‘activated’ since nearly 100% also expressed α-SMA (Fig1B)." (PMID 25834145, 2015). "Immunohistochemically, tumor cells were diffusely positive for Vimentin and CD99, focal positive for CD34, Bcl-2 and Actin, negative for CK, EMA, Desmin, CD117, GFAP, PR and S-100." (PMID 26155787, 2015). "In the present case, not only white blood cells but also the tumor cells of nephrogenic adenoma were positive for vimentin." (PMID 26428868, 2015).
tumor (continued). "More importantly, tumor tissues from LAD patients with high miR-214 expression showed high levels of vimentin and low levels of E-cadherin, whereas the reverse results were shown in miR-214 low expression groups (n = 6 paired)." (PMID 26462018, 2015). "Most tumor cell showed weak expression for vimentin and diffuse expression for BAF47(INI-1), and myogenin." (PMID 26208724, 2015). "Immunohistochemical staining revealed that the tumor cells were differentiated into fibroblastic and myofibroblastic, which are strongly positive for vimentin and SMA, and weakly positive for desmin and CD34." (PMID 26303928, 2015). "Immunohistochemical studies revealed that the tumor cells reacted with pan-cytokeratin immunostains and expressed vimentin and S-100 protein." (PMID 26943443, 2015). "In the tumor microenvironment, tumor cells downregulate E-cadherin expression and overexpress N-cadherin and vimentin, which weakens intercellular adhesive attractions and facilitates invasion and metastasis." (PMID 26170886, 2015). "Positive E-cadherin staining appeared in the cytomembrane or cytoplasm of tumor cells, positive N-cadherin staining was detected in the cytomembrane, and positive vimentin staining was present in the cytoplasm." (PMID 26702618, 2015). "Simultaneously, the OTSCC specimens were immunostained for several EMT-related proteins (E-cadherin, N-cadherin and Vimentin) that are potentially relevant to tumor EMT." (PMID 25762643, 2015). "Depletion of HNF4α is a critical determinant of epithelial-to-mesenchymal transition, characterized by loss of the epithelial marker E-Cadherin and induction of the mesenchymal marker Vimentin during tumor progression." (PMID 26157476, 2015). "Inhibition of miR-221 reduced uPAR protein expression and expression of the tumor cell invasion markers vimentin and RHOC." (PMID 25797271, 2015). "The tumor cells were positive for vimentin, alpha 1-antitrypsin, alpha 1-antichymotrypsin, and desmin, and partially positive for CD34 and alpha-SMA." (PMID 26366352, 2015). "Immunohistochemical (IHC) staining of the tumor was positive for both vimentin and smooth muscle actin (SMA)." (PMID 26187280, 2015). "High NEAT1 expression levels acts as a pivotal player in tumorigenesis and metastasis of HCC, LncRNA AOC4P is a tumor suppressor for HCC by enhancing vimentin degradation and suppressing the epithelial mesenchymal transition(EMT)." (PMID 26674525, 2015). "Western blot analysis revealed reduced levels of Ki67, pY397FAK, pAkt and vimentin but increased levels of cleaved caspase-3 in Agrin-depleted tumours." (PMID 25630468, 2015). "Taken together, our findings suggest that AOC4P lncRNA acts as an HCC tumor suppressor by enhancing vimentin degradation and suppressing the EMT." (PMID 26160837, 2015). "In non-tumor specimens, vimentin staining was noted in mesangial cells of the glomeruli with cytokeratin staining found in some, but not all, tubules." (PMID 26317980, 2015). "An important mechanism contributing to tumor cell invasion and migration is EMT, characterized by concomitant loss of epithelial markers and acquisition of mesenchymal markers such as vimentin in tumor cells." (PMID 26594799, 2015). "In order to confirm the observed nodules were derived from our injected tumor cells, immunohistochemical staining was performed by utilizing anti-human vimentin as well as anti-HOXA5 antibodies." (PMID 25875824, 2015). "Immunohistochemically, tumor cells were diffusely positive for vimentin and CD99, focal positive for CD34, bcl-2 and Actin." (PMID 26155787, 2015). "Within the tumor masses, abundant populations of vimentin and Transforming Growth Factor β1 (TGFβ1) positive tumor cells can be visualized." (PMID 25970777, 2015).
tumor (continued). "It has been reported that ectopic expression of vimentin and loss of CK, indicating EMT, in 2, 517 breast cancer patient samples was associated with a higher tumor grade and mitotic index." (PMID 26267323, 2015). "Another example is withaferin A, a tumor inhibitor and antiangiogenic agent that targets the vimentin protein." (PMID 26160837, 2015). "Vimentin, a member of the intermediate filament family of proteins, is ubiquitously expressed in mesenchymal cells, and expressing vimentin in cancer cells increases tumor growth and invasiveness." (PMID 25909322, 2015). "In particular, Raviraj and colleagues observed EMT in solitary primary tumour cells in dense collagen stroma, as these cells were positive for both vimentin and CK-19." (PMID 26040322, 2015). "Patients with elevated phospho-Src and vimentin have direct correlation with greater lymph node involvement and advanced tumor stage." (PMID 25734659, 2015). "Hypoxia significantly enhanced tumor cell migration, and invasive cells exhibited stronger vimentin expression than stationary cells." (PMID 25957416, 2015). "Immunohistochemical protein expression analysis at 2 weeks shows the downregulation of E-cadherin and β-catenin and enhanced vimentin expression in TGBC-LNs in comparison with BGC-neoplasia." (PMID 24845259, 2014). "After complete surgical removal of the tumor, immunohistochemical analysis revealed strong positivity for the mesenchymal markers vimentin, CD34, CD31 and CD99 in neoplastic cells." (PMID 24758544, 2014). "In SiHa-EGFP+ cells and tumor tissues, real-time PCR demonstrated that mesenchyme proteins such as vimentin, snail, and β-catenin were markedly upregulated at the mRNA level." (PMID 24489842, 2014). "The tumour cells showed strong diffused immunoreactivity for vimentin, synaptophysin, CD56 and inhibin." (PMID 24602387, 2014). "In our pilot study, we detected the expression of 4 proteins which were closely related with the invasive potential of tumor cells, including vimentin, RhoA, RhoC and MMP-2." (PMID 24658581, 2014). "Within solid tumors in general, vimentin expression correlates with accelerated tumor growth, increased metastatic potential, and poorer prognosis." (PMID 25162558, 2014). "The overexpression of Vimentin in cancers is known to correlate with accelerated tumor growth, invasion, and poor prognosis." (PMID 24959847, 2014). "viii) A high abundance of fibroblasts (L1) in the tumoral stroma correlated with increased L1CAM expression in the carcinoma cells (P2) and high numbers of CD68+ (H1) and CD163+ (I1) macrophages correlated with elevated vimentin expression in tumor cells (R)." (PMID 24797069, 2014). "Immunohistochemically, the tumor cells coexpressed an epithelial marker (cytokeratin), a mesenchymal marker (desmin and vimentin), chromogranin A, and cluster of differentiation (CD) antigens, CD99 and CD56." (PMID 25289084, 2014). "The tumor cells were diffusely positive for S-100 protein, strongly positive for vimentin, and focally positive for BCL-2 and CD57." (PMID 25364450, 2014). "Treatment of HCT116 tumor microenvironment co-cultures with curcumin down-regulated the expression of vimentin, whereas it increased E-cadherin levels." (PMID 25238234, 2014). "Vimentin is one of the major mesenchymal intermediate filaments and its expression represents the completely dedifferentiated state in tumor cells that are highly proliferative and invasive." (PMID 25245189, 2014). "There was downregulation of E-cadherin and upregulation of vimentin in the tumor cells that were previously cocultured (separated by a transwell insert) with myeloid cells." (PMID 24652403, 2014). "Tumor cells in vivo showed important myoepithelial markers such as vimentin, S-100 protein, cytokeratin and smooth muscle actin." (PMID 25137137, 2014).
tumor (continued). "E-cadherin and Vimentin are known to be associated with the epithelial mesenchymal transition (EMT), which is a key point in tumor progression and generally participate various cells migration and invasion." (PMID 25405202, 2014). "The tumour and the precancerous change were endometrioid expressing vimentin and oestrogen receptor." (PMID 24527040, 2014). "In contrast, immunoblotting analysis of HCT116 tumor microenvironment co-cultures treated with 5-FU showed marked dose dependent up-regulation of vimentin, but down-regulation of E-cadherin." (PMID 25238234, 2014). "Immunohistochemical study showed that the tumor cells were strongly positive to vimentin, α-smooth muscle actin, and muscle specific actin and negative to CD34." (PMID 25143851, 2014). "Different cytoplasmic proteins are key in the transformation of a normal cell to an invasive tumor cell and among these, vimentin is particularly important." (PMID 24527079, 2014). "Western blot analysis of E-cadherin and vimentin in tumor lysates and E-cadherin immunohistochemical staining of the tumors confirmed that the EMT status was retained in tumors formed by miR-100-expressing HMLE-Erbb2 cells." (PMID 24586203, 2014). "Next, to determine if GLUT3 knockdown had an impact on the mesenchymal state of tumor cells, we monitored vimentin and E-cadherin expression." (PMID 25097756, 2014). "Immunohistochemical examination brings evidences to support the diagnosis: the tumor expresses vimentin and smooth muscle actin." (PMID 25408738, 2014). "The present study was conducted to evaluate the role of cell adhesion molecules β-catenin, E-cadherin and vimentin in predicting tumour metastasis of OSCC." (PMID 25047112, 2014). "Semiquantitative immunohistochemistry was used to examine the expression of epithelial markers (E-cadherin and β-catenin) and mesenchymal marker (vimentin) in 104 lung SCC tumor tissues." (PMID 24758906, 2014). "Immunohistochemical staining with antibodies against vimentin, inhibin, α-smooth muscle actin and the α-helical rod domain of desmin was performed to confirm the diagnosis of this rare tumor." (PMID 25360170, 2014). "For this, a portion of each tumor was first subjected to Western blot analysis with anti-vimentin antibody." (PMID 25162558, 2014). "These similarities are compatible with the development of human GBM tumor, as also indicated by the presence of human vimentin-positive cells in the entire tumor mass." (PMID 25482099, 2014). "In Colo699 mono- and co-cultures vimentin was already expressed after five days with a slight upregulation in the co-cultured tumour cells." (PMID 24663399, 2014). "It is known that EMT is a process associated with many factors, of which TGF-β, Vimentin, ZEB-1, SMAD-7, E-cadherin and N-cadherin molecules are closely associated with the typical phenotype change of EMT in the process of tumor cell growth." (PMID 24625224, 2014). "For that reason, we further characterized the serosal tumors by immunofluorescence (IF) for vimentin, cytokeratin and podoplanin in at least one tumor from each affected mouse." (PMID 24405760, 2014). "Immunohistochemistry showed that the tumor spindle cells were positive for vimentin, CD68, CD45, and Ki-67 (labeling = 18%), α-smooth muscle antigen, and NSE." (PMID 25379319, 2014). "Downregulation of tuberin resulted in decreased expression of N-cadherin and increased expression of vimentin in tumor tissues of TSC-patient kidneys." (PMID 25149531, 2014). "In brief, each TEM-1 associated biomarker was combined with DAPI to identify nuclei, cytokeratin (CK) to identify tumor membrane/cytoplasm, vimentin to identify stroma and CD31 to identify vasculature." (PMID 24980818, 2014). "It is well known that vimentin is a prominent member of the intermediate filament family of proteins whose overexpression in cancer correlates well with increased tumor growth, invasion, and poor prognosis." (PMID 24797520, 2014).